CCR7 (C-C motif chemokine receptor 7)
Diseases named in the same sentence as CCR7 in open-access papers (continued):
Sharing a sentence is not in itself a finding about the gene and the disease.
tumor (continued). "The main chemokines involved in oral carcinogenesis, tumor invasion and metastasis are CCR4, CCR5, CCR7 and CXCR4, and our aim was to evaluate the prognostic value of the immunoexpression of these chemokines in SCC of tongue and floor of the mouth." (PMID 31011147, 2019). "IL6, can prevent dendritic cell maturation, prime tumor-specific T-cells via signal transducer and activator of transcription 3 (STAT3) signaling, inhibit NF-κB binding activity, and inhibit C-C chemokine receptor type 7 (CCR7) expression." (PMID 29486723, 2018). "We defined the differentiation stage of the different lung and tumor T cell subsets by analyzing the surface expression of CD45RA, CD28, CD27, and CCR7." (PMID 30505306, 2018). "Th17 cells, mostly mediating potent antitumor immunity by recruiting CD8+ T cells, NK cells, and dendritic cells (DCs) into the tumor microenvironment, express high levels of CCR6 and CXCR4 and low levels of CCR7." (PMID 30591657, 2018). "Furthermore, it may modulate the movement and escape of CCR7+tumor cells achieving metastasis." (PMID 28416768, 2017). "Given that data suggests CCR7 selected T cells display multiple characteristic characteristics of early-differentiation status we tested whether this led to enhanced engraftment and reduction in tumour growth in the severely immunodeficient NSG (NOD/SCID IL-2Rγ-/-) mouse strain." (PMID 28239467, 2017). "CCR7 expression in the RCC sample was variable, and mostly on the membrane and cytoplasm of tumor cells." (PMID 28114889, 2017). "These processes mostly accompanied with tumor cell migration and matrix metalloproteinase-9 (MMP-9) mediated extracellular matrix degradation, which was similar to the CCR7 mediated lymph vessel intravasation process." (PMID 28114889, 2017). "Thus, our studies elucidating the CCR7 could be a novel target for tumor therapy." (PMID 28378417, 2017). "Through suppression of CCR7 in an LXR-dependent manner, oxysterols impede host anti-tumour immunity." (PMID 27341022, 2016). "Among 20 proteins in the CCR7 signaling pathway sorted using EGAN and KEGG software, 18 were involved in crosstalk with EMT, drug resistance and tumor stem cell signal pathways." (PMID 26176983, 2015). "Although breast cancer cells also express chemokine receptors including CCR5, CCR7 and CXCR4 that enhance tumor cell invasiveness and metastasis, it is unlikely that a single treatment with chemokine antagonist can directly induce tumor cell death." (PMID 26275794, 2015). "We next determined the memory phenotype using the lymph node-homing chemokine receptor marker CCR7 together with CD45RA to further characterize the phenotype and the function of tumor-specific SLN-T cells." (PMID 25990075, 2015). "At first, quantitative real-time PCR was employed to compare the expression profile of CCR7, CCL21, and VEGF-C in primary tumor and adjacent breast tissues (control)." (PMID 25744065, 2015). "Flow cytometric analysis of the harvested tumor lysate-loaded DCs revealed a phenotype characteristic of mature DCs with high expression of CD40, CD80, CD83, CD86, HLA-ABC, HLA-DR, and CCR7." (PMID 25694811, 2014). "Whereas naive T cells (CD45RA+CCR7+) make up about 25% of T cells in the peripheral blood of CRC patients and healthy controls their percentage in tumor samples is less than 10%." (PMID 25026291, 2014). "In our previous study, CCR7 was examined in 78 specimens by immunohistochemical staining, and it was demonstrated that CCR7 is highly expressed in SCCHN tissue and is correlated with tumor metastasis." (PMID 25405202, 2014). "It is possible that CCR7, CXCR4 and VEGF-C interact with each other in the process of the metastatic spread of tumor cells to distant regional lymph nodes." (PMID 23761820, 2013). "The present study is the first to detect the expression of CCR7, CXCR4 and VEGF-C in tumor tissues using real-time RT-PCR and immunohistochemistry assays in a large series of human PDAC specimens." (PMID 23761820, 2013).
tumor (continued). "High intra-tumoral levels of CCL20 result in the accumulation of immature CCR6+ DCs within the tumor bed, whereas high peri-tumoral levels of CCL19 promote the accumulation of mature CCR7+ DCs preferentially to the tumor margin." (PMID 24339824, 2013). "The tumor-infiltrating FoxP3+ T cells largely lack CD62L and CCR7, two trafficking receptors required for T cell migration into secondary lymphoid tissues." (PMID 22292042, 2012). "CCR7 and CD62L are the most important trafficking receptors for migration of T cells into secondary lymphoid tissues such as the tumor-draining lymph node." (PMID 22292042, 2012). "VEGF-C expressed by tumor cells and monocytes in the tumor stroma stimulates LEC production of CCL21, and CCL21 in turn activates its receptor CCR7 in cancer cells." (PMID 22505936, 2012). "These EMRA cells have been characterized as terminally differentiated CD8 T cells potentially able to home into inflamed tissues such as the tumor microenvironment because they have lost the CD62L and CCR7 lymphoid homing receptors." (PMID 20653948, 2010). "The amounts of CCR7 (Figure 1B2) and EGFR (Figure 1E2) were detected in 82% and 66% of tumor cells, respectively, in the cytoplasm and/or membrane." (PMID 20181250, 2010). "Infiltrating mononuclear cells and tumor cells both showed expression of the receptor CCR5, while CCR7 was predominantly expressed by the mononuclear infiltrate." (PMID 18215331, 2008). "Furthermore, PTT's thermal effects increase tumor vascular permeability and perfusion, facilitating immune cell infiltration and CXCR6+ and CCR7+ T‐cell recruitment, which collectively drive potent anti‐tumor immunity." (PMID 41298282, 2026). "Moreover, the presence of TLSs and the elevated expressions of CCR7 and VEGF-C in tumor tissues can serve as indicators of a favorable response to anti-PD-1 immunotherapy in HCC patients." (PMID 40685403, 2025). "In human tumours, we also observed an enrichment of CCR7 cDC1s but not CXCL9 cDC1s within TCF1 regions, which suggests that discrete spatial co‐localisation is preserved across species." (PMID 40745918, 2025). "At 48 hours post-treatment, an elevation in anti-tumor macrophage activation markers was observed, with increases in expression of MHCII, co-stimulatory markers CD86 and CD80, PDL1 and the migratory marker CCR7." (PMID 41048107, 2025). "Both CD45RA−CCR7− effector memory (EM) and CD45RA+CCR7− terminal effector memory (TEM) T cells, which dominate the tumor microenvironment, were increased, whereas CD45RA+CCR7+ stem cell-like memory (SCM) and CD45RA−CCR7+ central memory (CM) T cells were reduced." (PMID 40335738, 2025). "Of CD3+ T cells, the tumor had the highest proportion of CD8+ T cells (55.8% in tumor vs. 29.9% in MPE vs. 31.6% in blood), which were predominantly composed of CD45RA−CCR7− effector memory and CD45RA+CCR7− terminally differentiated (Temra) subsets." (PMID 41415427, 2025). "In this research, one unanticipated finding was that only blocking the CCR7 signal on HCCLM3 already showed significant tumor inhibition in HCC subcutaneous mouse models without sorafenib treatment." (PMID 40685403, 2025). "Additionally, we know from CD8+ T cell studies, that a central memory subset expressing the chemokine receptor CCR7 (CD197) and CD62L (L-Selectin) has been shown to be more effective at controlling tumor in vivo than an effector memory subset." (PMID 41369406, 2025). "The CCR7+ DC subpopulation also plays an important role in antitumor immunity, with mature DCs signaling via the chemokine CCR7 migrating from the TME to TDLNs, where they initially activate and expand tumor-specific T cells." (PMID 40385461, 2025). "By bypassing the requirement for CCR7-mediated lymph node homing and subsequent T cell activation, ISG+ DCs could accelerate antigen-specific anti-tumor responses and promote sustained DC-T cell interactions within the TME." (PMID 40977690, 2025).
tumor (continued). "CCR7 blockade with a function-blocking antibody significantly reduced KikGR-red cell influx into dLNs, resulting in impaired CD8+ T cell priming and diminished anti-tumor responses." (PMID 40606756, 2025). "Beyond exhaustion, T cells exist in multiple states including naive (CD45RA+CCR7+), central memory (CD45RO+CCR7+), effector memory (CD45RO+CCR7−), and terminally differentiated effector (CD45RA+CCR7−) populations, each with distinct capacities for tumor control." (PMID 40806379, 2025). "It is generally accepted that migratory DCs (e.g., cDC1) transport tumor antigens to LNs via specific chemokine receptors (e.g., CCL21/CCR7 signaling), which activate CD8+ T cells via cross-presentation, while the cDC2 subpopulation supports CD4+ T cell activation." (PMID 41281945, 2025). "The interaction of C–C motif chemokine receptor 7 (CCR7) with its ligand chemokine C–C motif ligand 21 (CCL21) drives the migration and accumulation of cross-presenting DCs in the lymph nodes, leading to T cell priming and tumor rejection." (PMID 41176596, 2025). "Notably, CCR7 expression in CD4+ T cells and B cells was varied individually in the peritumor and tumor tissues." (PMID 40685403, 2025). "Similarly, patients with a pCR were less likely to express CCR5, CCR7, CXCR4, and CXCR5 on tumors, and CXCR4 high expression (≥20%) on TILs in core biopsy tumor materials." (PMID 39001456, 2024). "Tumour-residing CCR7+ DCs co-localise with PD-1+CD8+ T cells in human and murine solid tumours, and following anti-PD-L1 treatment, upregulate stimulatory molecules including OX40L, thereby augmenting anti-tumour cytolytic activity." (PMID 38267413, 2024). "The results showed that RT increased the percentage of CD8+ positive CAR-T cells (CD3 + CD8 + EGFR + ) and effector CAR-T cells (CD3 + EGFR + CD45RA + CCR7-) in peripheral blood 7 days after CAR-T injection, highlighting the enhanced anti-tumor activity of the synergy therapy." (PMID 39578426, 2024). "Kaede-red, activated CCR7+PD-L2+ DCs, which were photo-labelled within the tumour and hence tumour emigrants, were readily detectable in the dLN, but not in the contralateral non-draining LN (ndLN)." (PMID 38267413, 2024). "TAMos derived from spleens of LLC tumor‐bearing mice markedly enhanced TCM cell differentiation as indicated by elevated percentages of CD44+CD62L+ T cells and increased levels of CD62L, CCR7, and IL‐7R expression during T cell antigen‐specific activation compared with vehicle or TANs." (PMID 38386350, 2024). "Given CCR7+ DCs are a major source of PD-L1 in tumours, and the marked response of CD8+ TEX cells to anti-PD-L1 treatment, we sought to identify CCR7+ DC-mediated interactions that might promote their activation and proliferation." (PMID 38267413, 2024). "The absence of OX40L expression in the dLN suggests that it is only upregulated by tumour-retained CCR7+ DCs, and that OX40L+CCR7+ DC do not emigrate to the dLN, or at least rapidly downregulate it upon tumour exit." (PMID 38267413, 2024). "Mature mDCs specifically expressed CCR7, CCL17 and CCL22 to recruit infiltrating T cells, which transduced immune signals and recruits peripheral T cells in TME with strong migration and regulatory capabilities, thus playing an anti-tumor role." (PMID 39256364, 2024). "Moreover, CXCR4 and CCR7 interact with their respective ligands chemokine (C-X-C motif) ligand 12 (CXCL12) and chemokine (C-X-C motif) ligand 21 (CCL21), enabling tumor cells to have “chemotaxis” and promoting their metastasis to the intended organs." (PMID 38549934, 2024). "Since CCR7+ DCs do not uniformly and instantaneously migrate to the dLN, and influence local tumour immunity, this activated DC subset cannot be unequivocally labelled as “migratory DC”." (PMID 38267413, 2024). "Since human cancer tissues are also present with CD83+CCR7- DCs, LXR inhibition may improve the tumor milieu in patients as well." (PMID 37833991, 2023).
tumor (continued). "In the draining lymph node, CCR7 transduced T cells were more abundant on day 4 but then slowly decreased over time, whereas CCR4 transduced T cells peaked at day 8, both in lymph node and tumor." (PMID 37301772, 2023). "CD8+ TMs expressing CCL5 and GZMA, MAIT (mucosal‐associated invariant T) cells expressing TCF7 and PLAC8, and CD4+ TNs (Naïve T cells) expressing CCR7 appeared in paratumour tissues, while CD4+ISG+ T cells expressing ISG15/20 and CD8+ TNs expressing TCF7 only appeared in tumour tissues." (PMID 36855810, 2023). "characterized “tumor-matching” T cells in the peripheral blood (i.e., T cells in the blood expressing tumor-specific TCRs) as cells that expressed a more effector phenotype with a decreased expression of genes GYPC, CCR7, LTB, and FLT3LG." (PMID 37122719, 2023). "Although ceRNA network has been verified in a variety of tumor cells, the ceRNA network of CCR7/CCL19 chemokine axis in BC has not been studied." (PMID 37864213, 2023). "The expression by tumor-infiltrating NK cells of certain chemokine receptors including CCR2, CCR5, CCR7 and CX3CR1, and the abundance of their respective ligands in the TME has been correlated to enhanced NK cell tumor infiltration and improved cytotoxic response." (PMID 37298470, 2023). "However, we detected a small population of PD1+CCR7+ CAR-T cells, which was significantly decreased in the tumor samples collected at later time points." (PMID 36906640, 2023). "Similarly, the upregulation of CCR7, XCR1, MHC-II molecules and CD86 on cDC1 was observed upon BCL2 inhibition with venetoclax in the MCA205 tumor model." (PMID 37623817, 2023). "However, the function of the CCL19, CCL21/CCR7 and CXCL13/CXCR5 axes in tumor immunity is complicated." (PMID 37215990, 2023). "The levels of PD1 on CD8+ T cells were elevated in mice bearing MC38 VPS OE tumors, while CD44, CD107, CD62L, and CCR7 expression were not significantly different in either spleens or allografted tumor tissues." (PMID 36458816, 2022). "These pDCs expressed the lymph node–homing chemokine receptor CCR7 (data not shown), which was not evident in normal skin, consistent with ongoing tumor-antigen presentation." (PMID 36074574, 2022). "By contrast, MITF, CCR7, JAK1, ELN, and SLC6A4 were lowly expressed in tumor tissues." (PMID 36425071, 2022). "Among cases of oral and oropharyngeal squamous carcinoma cases, approximately 65% were positive for CCR7, which correlated with tumor progression, large lymph node metastases and reduced survival; normal oral mucosa was negative for CCR7 staining." (PMID 35203305, 2022). "Importantly, most of BRGs (25/28) in BRGPs signature, except CCR7, HERUD1 and SEC11C, were differently expressed among NSCLC tumor and normal tissue." (PMID 36389757, 2022). "CCL19 binds to CCR7 on a multitude of cell types including DCs and T-cells, whereas CXCL10 is a is a canonical chemokine for attracting T-cells, and its upregulation is correlated with smaller tumor size." (PMID 36741387, 2022). "A satisfactory tumour growth inhibition effect was observed in the PTX and PTX+CCR7 mAb groups." (PMID 35280672, 2022). "Higher CCR7 and CCL19 mRNA expression levels were observed in tumor tissue compared to control." (PMID 35160116, 2022). "Our study on the CCL19/CCR7 axis showed higher levels of CCR7 mRNA expression in NSCLC samples compared to macroscopically unchanged lung tissue (control tissue), surrounding the tumor." (PMID 35160116, 2022). "In addition, Niu and colleagues equipped a murine MΦ cell line with anti-CCR7 CARs designed to target an immunosuppressive subpopulation in the TME, which led to the inhibition of tumor growth and the prevention of metastasis in vivo." (PMID 35326445, 2022). "Importantly, UCB T cells also mount more effective antitumor responses via faster tumor infiltration with CCR7+ CD8+ T cells and faster induction of cytotoxic CD8+ T cells and CD4+ Th1 cells in the tumor microenvironment." (PMID 35365224, 2022).
tumor (continued). "T25 exhibited increased expression of PD-1, CTLA4 and low expression of CCR7, CD45RA, CD127 and CD28, consistent with previous studies that a subset of tumor-reactive CD8+ TILs were positive for CD103 and CD39 and exhibited an exhausted tissue-resident memory phenotype." (PMID 36311750, 2022). "In addition to this mechanism, tumor cells respond to the chemokine CCL21, which facilitates chemotaxis in CCR7+ expressing cells." (PMID 36158182, 2022). "However, if located on cancer cells, CCR7 and its ligands (CCL19/CCL21) is a vital axis for carcinogenic properties, such as epithelial-mesenchymal transition (EMT) tumor invasion and migration." (PMID 35938006, 2022). "The low intracellular content of ROS is related to the enhanced expression of the homing receptors CCR2, CXCR3 and CCR7, which promote both entry and accumulation of CLL cells in the pro-survival tumor microenvironment of lymphoid organs, eventually enhancing leukemic cell survival." (PMID 35847884, 2022). "In addition, the high expression of CCR7, CCL21 inhibited the function of dendritic cells and hindered the killing effect of T cells on tumor cells." (PMID 35309316, 2022). "CCR7 is a pivotal chemokine receptor for cell migration to secondary lymphoid organs, thus it is not surprising that tumor metastasis to lymph nodes was elevated when CCR7 expression was enhanced for all types of cancer." (PMID 35203305, 2022). "BM-DCs that express dysfunctional β2-integrin have enhanced tumor rejection capabilities in B16.OVA and B16-F10 melanoma models and higher levels of expression of CD86, Il12, ccr7, and Fscn1, which are indicative of improved co-stimulation and migration capacity." (PMID 35267487, 2022). "At the molecular level, combination therapy dramatically increased the number of MART1-specific CD8+ T cells in the tumor and frequency of memory precursor CD62L+/CD45RO+/ CCR7+CD8+ T cells in the spleen, which coincided with enhanced IFN-γ production by tumor antigen-specific CD8+ T cells." (PMID 33430239, 2021). "In this regard, CCR7-negative TEFF and TEM rather than CCR7-expressing TN or TCM are necessary for effective anti-tumour responses." (PMID 34778050, 2021). "Finally, CCR7 not only directs migration of leukemic cells in CLL but, in addition, it is needed for migration of non-tumor subsets such as T cells." (PMID 33841445, 2021). "For example, some anti-apoptotic proteins such as Bcl-2 have been correlated with increased CCR7 expression in other tumor diseases and in non-tumor CD8+ T cells." (PMID 33841445, 2021). "F4/80- and CCR7-positive staining within tumours was scored as either none/minimal or few/scattered." (PMID 33761981, 2021). "In contrast to other tumor entities, neither CCR7 protein nor mRNA expression significantly impacted patients’ survival." (PMID 34830848, 2021). "Surprisingly, even though CCR7 is required for lymphatic egress during acute inflammation, recent studies indicated that there is no CCR7 dependency in chronic inflammation and in tumor growth." (PMID 34065513, 2021). "A first report found no function for CCR7 in promoting in vitro survival or proliferation of primary SS tumor cells." (PMID 34778050, 2021). "Given that CCR7 did not significantly influence survival of patients with ACC and its expression in other adrenal tissues, it is probable that CCR7 plays a role in adrenocortical homeostasis rather than tumor invasion and progression in ACC." (PMID 34830848, 2021). "Interestingly, in non-tumor cells, COBLL1 expression was also found to be higher in GC B cells than naïve and memory subsets, where a marked reduction in CCR7 expression is needed to facilitate CXCR5-guided access to the GC." (PMID 33841445, 2021). "Epithelial cells from early tumours were unresponsive to any treatment suggesting that neither CXCR4 nor CCR7 in these cells can transduce the signal from their ligands." (PMID 34685420, 2021).